MB (myoglobin)
Diseases named in the same sentence as MB in open-access papers (continued):
Sharing a sentence is not in itself a finding about the gene and the disease.
rhabdomyolysis (continued). "However, CK and myoglobin peaks are late markers of rhabdomyolysis severity, which makes them inappropriate to predict AKI early." (PMID 34559325, 2021). "Blood purification with Cytosorb® integrated into a high-flux dialyzer may be a useful tool for the elimination of myoglobin in critically ill patients with rhabdomyolysis." (PMID 33509234, 2021). "Third, admission myoglobin was a better predictor of severe rhabdomyolysis than admission CK." (PMID 34559325, 2021). "We consider these results of importance, since CK and myoglobin are both regularly measured in the setting of rhabdomyolysis and choosing one over the other may thus lead to better AKI prediction." (PMID 34559325, 2021). "Admission myoglobin was better than CK at predicting development of significant rhabdomyolysis." (PMID 34559325, 2021). "Ferrous myoglobin was applied to HKC-8 cells to induce an in vitro model of rhabdomyolysis." (PMID 33202867, 2020). "Moreover, kidneys can be impaired when extreme levels of myoglobin are released, known as rhabdomyolysis." (PMID 31151484, 2019). "When the basal membrane and sarcolemma of the injured muscle fibres are compromised (such as in rhabdomyolysis), the consequential result is that cytoplasmic components, such as myoglobin and creatine kinase (CK), are released from the injured muscle fibres into the blood stream." (PMID 31304016, 2019). "Rarely, hypothyroidism may be complicated by rhabdomyolysis, the rapid destruction of skeletal muscle with myoglobin, creatine kinase, urate, and electrolytes release into the circulation." (PMID 31403010, 2019). "Moderate to severe rhabdomyolysis may result in myoglobinuria, metabolic alkalosis and azotaemia due to the effects of the myoglobin on the kidneys." (PMID 31304016, 2019). "It is also now evident that, using a rhabdomyolysis mice model, myoglobin released from damaged muscle may increase vasoconstriction within the renal afferent arterioles." (PMID 31304016, 2019). "Individuals who experience severe muscle damage may present with exertional rhabdomyolysis which is characterized by the continued release of myoglobin (Mb) into the circulation." (PMID 30804809, 2019). "In the current study, HIIRT induced early and progressive muscle injury, as shown by the muscle soreness, and significant changes in serum CK and myoglobin in the majority of the individuals assessed, with CK elevation indicative of rhabdomyolysis in 19% of the participants." (PMID 30399190, 2018). "Rhabdomyolysis is a clinical and laboratory syndrome, which refers to the changes in the integrity of the striated muscle cell membrane which leads to the release of a large number of myoglobin, CK, and small molecular substances into the peripheral blood." (PMID 30407314, 2018). "Consistent with our hypothesis, a significant amount of myoglobin released from damaged muscle cells is reabsorbed into the proximal tubule cells after its glomerular filtration in rhabdomyolysis." (PMID 28704479, 2017). "A presumptive diagnosis of rhabdomyolysis is based on the detection of increases in the activity of creatine kinase (CK) (at least 5 times that of the normal level) in the plasma, or the presence of myoglobin in the urine." (PMID 28018795, 2016). "On the other hand, it has been hypothesized that direct invasion of muscles or over production of myotoxic cytokines by dengue virus (DENV) causes rhabdomyolysis and AKI might be resulted due to accumulation of myoglobin in kidneys." (PMID 26421839, 2015). "Cellular destruction may also lead to the release of myoglobin into the circulation, and later rhabdomyolysis, renal failure, and even death may result." (PMID 23573335, 2013). "In a small group of 30 ICU patients with massive rhabdomyolysis, receiver operating characteristic analysis showed that the AUC for blood myoglobin that predicted acute renal failure was 0.88, and the best cutoff value for blood myoglobin was 3865 μg/l." (PMID 23497406, 2013).
rhabdomyolysis (continued). "This was complicated by rhabdomyolysis with raised serum and urine myoglobin but normal CK." (PMID 23256803, 2012). "Among these effects, rhabdomyolysis is a serious and potentially life-threatening complication, characterized by the breakdown of skeletal muscle and the subsequent release of intracellular contents—including creatine kinase (CK) and myoglobin—into the bloodstream." (PMID 40909457, 2025). "CytoSorb® (CS), is a CE-marked blood purification technology for the removal of cytokines, bilirubin and myoglobin, and may therefore be a valuable treatment option in patients with severe rhabdomyolysis; CS works by primarily removing hydrophobic substances from the bloodstream via hemoadsorption." (PMID 41398626, 2025). "Therefore, myoglobin exhibits low sensitivity for the diagnosis of rhabdomyolysis." (PMID 38256366, 2024). "Older studies define rhabdomyolysis on the basis of elevated serum creatinine kinase (CK), but serum myoglobin concentrations above between 368 μg/l and 3865 μg/l predict development of AKI more accurate and might be a better diagnostic parameter in view of myoglobin as nephrotoxic substance." (PMID 38486159, 2024). "However, when the myoglobin concentration exceeds the reabsorbing capacity of the kidney, myoglobulin appears in the urine (myoglobinuria) and when detected in the first 24 h after an injury, is pathognomonic for the diagnosis of rhabdomyolysis." (PMID 39085790, 2024). "Furthermore, the study in the Zurich Burn Center predicted that the development of compartment syndrome, rhabdomyolysis, high myoglobin and CK blood levels, kidney failure, sepsis, and respiratory complications during the hospital course were predictive of a higher amputation rate." (PMID 39599939, 2023). "In intense competitions, the severe rupture of muscle tissue (rhabdomyolysis) releases toxic intracellular components into the systemic circulation, which leads to an overload of renal tubules, heat stress, and intense sympathetic nerve activity due to myoglobin." (PMID 35324651, 2022). "Exertional rhabdomyolysis (ER) is a pathophysiological condition described by damage to or necrosis of the striated muscle tissues during strenuous exercise leading muscle cell disintegration enabling the release of myoglobin (Mb) into the bloodstream and extracellular space." (PMID 36554767, 2022). "In rhabdomyolysis, patients may present with muscles pain or weakness, red to brown color of urine (due to myoglobinuria) and markedly elevated creatine kinase (CK) and myoglobin levels." (PMID 34804738, 2021). "Second, unlike CK, myoglobin release does not depend on lymphatic transport and is faster released into the bloodstream, which makes it more accurate as an early marker for risk stratification of rhabdomyolysis-induced AKI." (PMID 34559325, 2021). "Therefore, RIG-I is a novel sensor for myoglobin in the CS-AKI model, and myoglobin-induced RIG-I/NF-κB/caspase-3 axis activation may contribute to the development of CS or rhabdomyolysis nephrotoxicity." (PMID 34148549, 2021). "Free Hb from lysed RBCs and myoglobin released from damaged muscle cells are inherently toxic molecules in the blood stream due to their intrinsic peroxidase activity and have been demonstrated to contribute to pathogenesis in hemolytic diseases and rhabdomyolysis, respectively." (PMID 29081812, 2017). "In this study, oestrogen prevented the ovariectomy augmented elevation of plasma CPK, myoglobin and myoglobin accumulation in renal tubules, indicating that oestrogen provides protection against LPS‐induced rhabdomyolysis and may contribute to improvement of renal function." (PMID 28714586, 2017). "There are no studies that determine the clinical effects of elevated serum myoglobin in degenerating fibroids; however studies involving rhabdomyolysis-induced renal failure suggest that a peak myoglobin level of around 4000 ng/mL might be a good predictor of ARF." (PMID 27375910, 2016).
rhabdomyolysis (continued). "The initial presentation was marked by severe rhabdomyolysis, as evidenced by elevated CPK and myoglobin levels." (PMID 40688837, 2025). "We present a case of slowly progressive rhabdomyolysis following SARS-CoV-2 infection in a 28-year-old male who was monitored through serial serum creatine kinase (CK) and myoglobin levels." (PMID 39347295, 2024). "The prospective Cyto-SOLVE study (NCT04913298) included 20 intensive care unit patients with severe rhabdomyolysis (plasma myoglobin > 5000 ng/ml), RRT due to acute kidney injury and the use of CS for myoglobin elimination." (PMID 38907120, 2024). "A high incidence of rhabdomyolysis and elevated serum myoglobin levels predict AKI, particularly with admission values above 1200μg/L or peak myoglobin levels above 5000 μg/L." (PMID 39202747, 2024). "Here, we present a case of slowly progressive rhabdomyolysis after SARS-CoV-2 infection in which serial measurements of serum CK and myoglobin levels were conducted." (PMID 39347295, 2024). "Results showed an increased value for creatinine kinase (CK) and myoglobin, which were > 22,000 μL and 1,902 ng/mL, respectively, which led to a diagnosis of AKI secondary to rhabdomyolysis." (PMID 36891010, 2023). "There was also a reported case of myeloperoxidase-vasculitis and rhabdomyolysis after Pfizer-BioNTech COVID-19 mRNA vaccination, whose biopsy demonstrated PICGN in addition to a severe acute tubular lesion with myoglobin cast and interstitial inflammation." (PMID 36544502, 2022). "Admission myoglobin better predicts the development of AKI and severe rhabdomyolysis after major trauma." (PMID 34559325, 2021). "We aimed to compare the ability of admission myoglobin and CK to predict AKI and severe rhabdomyolysis in trauma patients." (PMID 34559325, 2021). "Our study demonstrated the increased phosphorylation of IκB and the elevated expression of p65 in the injured kidneys of rhabdomyolysis-induced AKI and in myoglobin-induced HK-2 cells." (PMID 31639165, 2019). "In rhabdomyolysis-induced AKI, myoglobin plays the key role in leading to renal toxicity through multiple deleterious effects including tubular obstruction by myoglobin-derived casts, oxidative stress, inflammation, apoptosis and vasoconstriction." (PMID 31639165, 2019). "We also examined the protective effects of FABP4 inhibitor on the renal proximal tubular cell, the main injury site of rhabdomyolysis-induced AKI, using an in vitro myoglobin stimulation." (PMID 30135658, 2018). "Increased circulating levels of myoglobin and creatine phosphokinase (CPK) (i.e., CK-MM form) are common biomarkers found after acute rhabdomyolysis." (PMID 29805730, 2018). "We next investigated myoglobin-induced apoptosis in HK-2 cells in vitro to discover the mechanisms of the PI3K/Akt pathway and apoptosis pathway involved in rhabdomyolysis-relatedAKI." (PMID 28117405, 2017). "In this study, we found that HO-1 was significantly up-regulated at both gene and protein levels in rhabdomyolysis-induced AKI at all time points, indicating that HO-1 was a rapid response factor to myoglobin in renal tissues in vivo." (PMID 26987113, 2016). "Moreover, rhabdomyolysis was first wrongly ascribed to the strenuous exercise and/or to paracetamol therapy, but after a more detailed clinical history in our patient creatine phosphokinase and myoglobin elevation were found to occur after the development of the anasarcatic state and not before." (PMID 25738482, 2015). "Early diagnosis of rhabdomyolysis requires demonstration of elevated levels of serum CPK and urinary myoglobin." (PMID 23889764, 2013). "Serum myoglobin levels peak well before serum CPK levels, but, given its fast clearance, it has low sensitivity for the diagnosis of rhabdomyolysis." (PMID 23889764, 2013).
rhabdomyolysis (continued). "The laboratory tests revealed that the concentration of serum creatine kinase (CK) and myoglobin increased and acute renal failure symptoms were present, which provided an exact diagnosis for SAP-induced rhabdomyolysis." (PMID 23251265, 2013). "We now describe the use of SHF hemofiltration in a patient with severe rhabdomyolysis and oliguric ARF secondary to serotonin syndrome, and report on the kinetics of myoglobin clearance using both conventional and SHF hemofiltration." (PMID 15774055, 2005). "Indeed, an adult literature reported that at 3 months after rhabdomyolysis, the severity of AKI and high serum myoglobin levels were related with a decrease in estimated glomerular filtration rate, suggesting a potential kidney damage." (PMID 41146051, 2025). "The role of extracorporeal removal of myoglobin in the treatment of rhabdomyolysis is not yet fully established." (PMID 39375217, 2025). "Given the patient's prolonged deep sedation and coma, which precluded muscle strength testing, we diagnosed rhabdomyolysis based on elevated CK and myoglobin levels, rather than categorizing it as ICU-AW." (PMID 41246626, 2025). "Notably, there was severe hyperglycemia, metabolic acidosis with an elevated anion gap and high ketones, B-hydroxybutyrate, acute kidney injury, and markedly elevated CPK and myoglobin levels, supporting the diagnoses of DKA and rhabdomyolysis." (PMID 41287729, 2025). "Patient data, including patients’ demographic variables (sex and age), mode of arrival, final diagnosis, statin use, rhabdomyolysis trigger factors, and levels of serum creatine phosphokinase (CPK), myoglobin, creatinine, sodium, potassium, phosphate, calcium, and lactate, were analyzed." (PMID 38256366, 2024). "In fact, patients without the need of RRT had the highest rate of myoglobin reduction, so preserving patients ́ own renal function should be the primary goal in patients with rhabdomyolysis." (PMID 38907120, 2024). "In addition, our previous findings indicated that TPE + CRRT can reduce the levels of inflammation mediators (IL-8 and tumor necrosis factor-α) and markers of rhabdomyolysis (CK, LDH, and myoglobin)." (PMID 38376456, 2023). "The increase of myoglobin found here in PA patients was not as high as in acute myocardial injury or rhabdomyolysis, and it did not reflect acute muscle injury." (PMID 35265036, 2022). "Typically of rhabdomyolysis, our patient tested strongly positive for blood in the urine dipstick test (inability of the dipstick test to differentiate between hemoglobin and myoglobin) but without a significant RBC count." (PMID 34579193, 2021). "In contrast, myoglobin levels did not relevantly change in patients with increasing CK and therefore ongoing rhabdomyolysis (n = 22, median relative reduction 4%)." (PMID 33509234, 2021). "We assumed that myoglobin elimination by CS therapy was not visible in laboratory measurement due to persistent rhabdomyolysis with accumulation of further myoglobin and CK." (PMID 33509234, 2021). "In the 80 patients with available eGFR values both before and 3 months after the rhabdomyolysis, the decrease in eGFR (greater than 20 mL/min/1.73 m2 in 23 patients; 28.8%) was correlated to the severity of the AKI and serum myoglobin levels > 8000 U/L at admission." (PMID 32124091, 2020). "Rhabdomyolysis is a syndrome characterized by the breakdown of skeletal muscle and leakage of the muscle cell contents such as myoglobin into the bloodstream and acute kidney injury (AKI) is the most common and life-threatening systemic complication of rhabdomyolysis." (PMID 30135658, 2018). "Although exertional rhabdomyolysis is resolved without serious medical complications in most physical activity and sport situations, this condition can be fatal due to myoglobin-induced renal failure and/or cardiac arrhythmia, especially in hot environments." (PMID 28257486, 2017).
rhabdomyolysis (continued). "In the present study, we summarize two cases of SAP complicated by rhabdomyolysis in the Hepatobiliary Surgery Intensive Care Unit of the PLA General Hospital, Beijing, China, presenting with increased serum CK, increased myoglobin concentration and acute renal failure." (PMID 23251265, 2013). "Both myoglobin and CK-MB are usually used in diagnosing myocardial infarction but can also be significantly elevated due to noncardiac skeletal muscle injury (e.g., rhabdomyolysis) or renal failure." (PMID 41283479, 2025). "While dark brown urine due to myoglobinuria is a classic early indicator of rhabdomyolysis, studies have shown that up to 26% of patients with rhabdomyolysis may not have detectable levels of urinary myoglobin, as was observed in this case." (PMID 41356636, 2025). "In addition, unlike conditions such as hemolysis or rhabdomyolysis, where heme accumulation results directly from the release of hemoglobin or myoglobin from damaged cells, heme elevation in IRI primarily arises from intracellular cytochrome P450." (PMID 39766229, 2024). "These include the level of CK in isolation which could be used as a criterion for severe rhabdomyolysis although there was a majority agreement in terms of a value of > 5000 U/L being useful, particularly where myoglobin estimation is not readily available." (PMID 39085790, 2024). "In addition, unlike what is regularly stated, we think this study also supplies arguments to use myoglobin rather than CK to assess rhabdomyolysis severity in trauma patients." (PMID 34559325, 2021). "This also may be a reason explaining why myoglobin and CK are not interchangeable markers of rhabdomyolysis." (PMID 34559325, 2021). "Moreover, the markers of anaphylactic shock were not increased and there was no scientific evidence of rhabdomyolysis, based on the myoglobin biochemical examination and immunohistochemistry of the skeletal muscle." (PMID 30955048, 2020). "Moreover, the definite relationship between peak CK or myoglobin and ARF caused by different etiologies of rhabdomyolysis is not clear enough." (PMID 24004920, 2013). "However, rhabdomyolysis in our patient was rather mild at presentation (CPK 912 U/L) and myoglobinuria most probably played only a minor contributory role to AKI, even if scattered tubular myoglobin cylinders were detected in the renal biopsy taken on the day of admission." (PMID 39964593, 2025). "However, in the present case, there were no findings of rhabdomyolysis or myoglobin casts." (PMID 39720376, 2024). "Although no increased levels of creatine kinase and myoglobin were observed after two sets of resistance exercises with BFR, there are studies that report rhabdomyolysis." (PMID 38137705, 2023).